DRC10 (dynein regulatory complex subunit 10)
Description:
Component of the nexin-dynein regulatory complex (N-DRC), a key regulator of ciliary/flagellar motility which maintains the alignment and integrity of the distal axoneme and regulates microtubule sliding in motile axonemes.
Synonyms: IQCD; CFAP84; 4933433C09Rik
Tractability: Small molecule: a structure with a bound ligand is known. PROTAC: ubiquitination databases record sites on it.
Gene: Protein-coding gene on chromosome 12 (113,194,156 to 113,221,098, reverse strand). Ensembl gene ENSG00000166578.
Subcellular location: Cytoplasm, cytoskeleton, flagellum axoneme
Subcellular location (Human Protein Atlas): End piece; Mid piece; Principal piece
Gene Ontology:
Biological process: cilium movement; flagellated sperm motility
Cellular component: ciliary basal body; axonemal nexin link; axoneme
Genetic constraint (gnomAD): Loss-of-function variants: 25 observed, 33.59 expected, observed/expected ratio (o/e) 0.74, 90% interval 0.54 to 1.04. The upper end of that interval is the gene's LOEUF score, 1.04, which puts it in group 4 of 6, group 1 being the genes least tolerant of losing a copy. Missense variants: 470 observed, 543.84 expected, observed/expected ratio (o/e) 0.86, 90% interval 0.8 to 0.93. Synonymous variants: 182 observed, 213.43 expected, observed/expected ratio (o/e) 0.85, 90% interval 0.75 to 0.96.
Homologues: Orthologues: chimpanzee IQCD (99% identical), macaque IQCD (93% identical), pig IQCD (76% identical), dog IQCD (74% identical), guinea pig IQCD (67% identical), mouse Iqcd (67% identical), rat Iqcd (66% identical), rabbit IQCD (65% identical), tropical clawed frog iqcd (40% identical), zebrafish iqcd (33% identical).
Diseases named in the same sentence as DRC10 in open-access papers:
DRC10 is named in the same sentence as 1 disease in open-access papers, as found by Europe PMC text mining. Sharing a sentence is not in itself a finding about the gene and the disease.
DRC10 shares sentences with these, for which no sentence is quoted: glioma (1 paper).